TNF (tumor necrosis factor)
Diseases named in the same sentence as TNF in open-access papers (continued):
Sharing a sentence is not in itself a finding about the gene and the disease.
psoriasis (continued). "Other proinflammatory factors released by pathogenic Th17 cells, such as IL-22, TNF-α, and granulocyte-macrophage colony-stimulating factor (GM-CSF), stimulate keratinocytes to release chemokines, further sustaining the inflammatory cycle to promote the development of psoriasis." (PMID 29899748, 2018). "In addition to IL-17A, our study suggests that some pathogenic Tregs may also produce more TNF-α in psoriasis skin, potentiating the effects of IL-17A and contributing further to the inflammatory cascade." (PMID 30054515, 2018). "Our results suggest IFN-γ/TNF-α synergy may provide a critical pro-inflammatory link between psoriatic skin inflammation and distant vessel atherosclerosis, and identifies that potential blockade of both IFN-γ and TNF-α as a novel therapeutic target in psoriasis-associated atherogenesis." (PMID 29062018, 2017). "Furthermore, treatment of psoriasis patients with TNF-α inhibitors may improve biomarkers of cardiovascular risk." (PMID 29065479, 2017). "In addition, TNF-α inhibitor treatment may decrease the risk of diabetes mellitus in patients with psoriasis, and improve insulin sensitivity both in diabetic and non-diabetic patients." (PMID 29065479, 2017). "Our results are consistent with the hypothesis that increased IFN-γ and TNF-α in psoriasis is associated with a systemic pro-inflammatory gradient from inflamed skin, which then promotes inflammatory responses in both aortic endothelial cells and atherosclerotic tissue in a synergistic manner." (PMID 29062018, 2017). "Although possible associations of the TNF-α polymorphisms with psoriasis were reported, and many case-control studies were further performed to identify the association, it was still unknown whether there were significant associations of TNF-α 308 G/A and 238 G/A polymorphisms with psoriasis risk." (PMID 24324571, 2013). "Thus, TNF-α plays an important role in activating the expression of adhesion molecules on vascular endothelial cells and then causes the subsequent increased trafficking of leukocytes in psoriasis." (PMID 20877233, 2010). "Therapeutic targeting of TNF-α and IL-17 in psoriasis likely affects not only immune cells but also dermal fibroblasts, disrupting the inflammatory networks that sustain disease." (PMID 41598494, 2026). "Therapeutic blockade of IL-17 and TNF can effectively treat inflammatory skin diseases such as hidradenitis suppurativa and psoriasis, yet the relative importance of the different cell types that respond to IL-17 and TNF remains unresolved." (PMID 41929214, 2026). "Across all conditions, migration of inserted T cells towards the epidermis and the secretion of psoriasis-associated cytokines (IFN-γ, IL-17, TNF-α, IL-1β, CCL20, IL-6, and IL-10) was observed." (PMID 42039187, 2026). "Here, we demonstrate that intradermal injection of recombinant IL-17 and TNF elicits skin inflammation with features of hidradenitis suppurativa, including a gene expression program that is distinct from psoriasis and imiquimod-induced inflammation." (PMID 41929214, 2026). "A psoriasis-like cellular model was created by exposing HaCaT cells to TNF-α (50 ng/ml) for a duration of 24 h." (PMID 41873121, 2026). "In clinical practice, both Guselkumab and Risankizumab have demonstrated higher response rates in treating psoriasis than TNF inhibitors, offering more effective options for patients and elucidating the key role of IL-23 in psoriasis pathogenesis." (PMID 40536951, 2026). "This prospective study investigated the effects of brodalumab on serum cytokine levels—specifically IL-6, IL-17A, IFN-α, IFN-γ, and TNF-α—and their correlation with disease severity as assessed by Psoriasis Area and Severity Index (PASI)." (PMID 41516330, 2026). "TNF-α is an important proinflammatory cytokine in psoriasis pathogenesis that is released by immune cells and keratinocytes." (PMID 41516330, 2026).
psoriasis (continued). "In recent years, monoclonal antibodies targeting key cytokines underlying skin lesions and joint involvement in the course of psoriasis, i.e., TNF-α, IL-17, and IL-23, have been increasingly used due to their high effectiveness and favorable safety profile." (PMID 41684030, 2026). "Eighteen patients with moderate-to-severe psoriasis who were unresponsive to TNF-α inhibitors received brodalumab for 12 weeks." (PMID 41516330, 2026). "The main cytokines involved in the pathogenesis of psoriasis are certainly TNFα, IL-12, IL-17, and IL-23, whereas in the pathogenesis of AD, IL-4, IL-13, and IL-31." (PMID 41481132, 2026). "Biologics targeting IL-6, IL-17, and TNF-α have demonstrated efficacy in psoriasis, and their effects likely extend to fibroblast populations." (PMID 41598494, 2026). "In this study, we investigated serum levels of IL-6, IL-17A, IFN-α, IFN-γ, and TNF-α in patients with psoriasis before and after treatment with brodalumab, all of whom had previously failed therapy with TNF-α inhibitors." (PMID 41516330, 2026). "Here, a digital surface-enhanced Raman spectroscopy (SERS) immunoassay has been developed for multiplex detection of IL-17A, IL-22, IL-23 and TNF in punch biopsy skin using psoriasis as a model." (PMID 42124321, 2026). "This trend is noteworthy given the central role of TNF-α in inflammation, its established connection to the pathogenesis of psoriasis, and its relevance as a treatment target." (PMID 41516330, 2026). "In mice, topical imiquimod induces IL-17- and TNF-dependent skin inflammation and is frequently used to model psoriasis." (PMID 41929214, 2026). "Probiotics are associated with significantly reduced Psoriasis Area and Severity Index (PASI) scores, increased PASI 75 response rates, lowered inflammatory biomarkers (CRP, TNFα, IL-6) and improved Dermatology Life Quality Index (DLQI)." (PMID 42005309, 2026). "These responses mediated by TNF-α are involved in the pathogenesis of contact dermatitis, including atopy, psoriasis, and allergies." (PMID 41614914, 2026). "Immune class switching with other psoriasis biologics, such as TNF-alpha and IL-23 inhibitors, does occur, though it is documented less frequently than with IL-17i suggesting a less robust risk of immune deviation." (PMID 41446699, 2026). "Significant reduction in plasma CRP levels across all patient groups.TNF-α levels decreased significantly in psoriasis patients.Demonstrated systemic anti-inflammatory effects beyond the gut." (PMID 41277234, 2025). "It is a common model of induction of psoriasis as it activates the production of downstream factors like IL-6, IL-23, IL-1β, and TNF-α by binding to TLR-7 and stimulating epidermal plasma-like dendritic cells and macrophages." (PMID 40343294, 2025). "Central to the pathogenesis of psoriasis are dysregulated immune responses mediated by dendritic cells, Th1, Th17, and Th22 lymphocytes, and the overproduction of cytokines such as TNF-α, IL-17, IL-23, and IL-22." (PMID 40690118, 2025). "Over twenty years ago, psoriasis was originally considered as a Th1-type disease, in which IFN-γ and TNFα were the predominant pathogenic cytokines." (PMID 39861699, 2025). "Treatments involving Treg‐of‐B cells activate M2 macrophages via the STAT6 pathway, reducing TNF‐α and IL‐6 production and alleviating psoriasis symptoms in mice." (PMID 40539722, 2025). "According to the literature, the frequency of anti-TNF-induced autoimmunity ranges from 0.03% (demyelinating CNS events) to 10.7% (psoriasis)." (PMID 41142785, 2025). "Biologics have revolutionized the management of moderate-to-severe psoriasis by specifically targeting immune pathways involving tumor necrosis factor-alpha (TNF-α), interleukin-17 (IL-17), and interleukin-23 (IL-23)." (PMID 39860587, 2025). "Th17 cells are directly affected by TNF-α in psoriasis, because it decreases autonomous TNF/TNFR2 signaling." (PMID 40690118, 2025).
psoriasis (continued). "Clinical studies have reported that patients with psoriasis exhibited significantly elevated serum levels of TNF-α, averaging 362.67 ± 456.9 pg/mL, compared to 14.64 ± 5.78 pg/mL in healthy controls." (PMID 40733073, 2025). "The impact of IL-17A on psoriasis is modest by itself, but its significant influence in the disease’s development and progression is enhanced through synergy with TNF-α, IL-22, and IFN-γ." (PMID 40303401, 2025). "Visfatin has regulatory properties in cell proliferation and apoptosis and has also been shown to induce TNF-α-induced chemokine secretion in human keratinocytes, linking it to psoriasis pathophysiology." (PMID 40584532, 2025). "In psoriasis, TNF-α as well as IFN-γ modulate keratinocyte apoptosis by changing expression balance between Bax which is a pro-apoptotic protein, and Bcl-xL which is an anti-apoptotic regulator, result in initiating programmed cell death." (PMID 40818978, 2025). "For instance, MSCs have been shown to inhibit T helper (Th) 17 cell proliferation and reduce the production of pro-inflammatory cytokines such as IL - 17 and TNF-α, which play a pivotal role in psoriasis pathogenesis." (PMID 40969757, 2025). "Biologics targeting tumor necrosis factor-α (TNFi), interleukin-12/23 (IL-12/23i), and interleukin-17 cytokine or receptor (IL-17i/IL-17Ri) have transformed psoriasis management." (PMID 41009564, 2025). "These cytokines are part of the TNF/IL-23/IL-17 axis, a well-established inflammatory pathway in psoriasis." (PMID 41008526, 2025). "Martina Morelli also found that IL-6 and TNF-α are aberrantly expressed in psoriasis reactions induced by anti-PD-1, at levels comparable with chronic psoriasis." (PMID 40936709, 2025). "In psoriasis lesions, TNF-α exhibits pro-inflammatory properties that stimulate IL-12 and IL-18 production, influencing Th1 immune responses." (PMID 40303401, 2025). "Tumor necrosis factor blockers have been reported to induce paradoxically inflammatory psoriasis and/or lichen psoriasis." (PMID 39963435, 2025). "Cytokines like IL-17A, IL-22, IL-23, and tumor necrosis factor-a (TNF-α) play a role in psoriasis pathogenesis." (PMID 40343294, 2025). "That study, which used a high-throughput SomaScan assay on patient serum, reported SLFN5 as one of the proteins elevated in psoriasis patients–particularly tied to TNF-α and interferon-driven inflammation." (PMID 41328434, 2025). "Ιn psoriasis, the Th17-driven inflammatory response, characterized by elevated levels of IL-23, IL-17, and TNF-α, is amplified during COVID-19 infection, triggering disease flares." (PMID 41011460, 2025). "Both drugs help in the treatment of psoriasis and pemphigus vulgaris through inhibition of tumor necrosis factor-alpha (TNF) synthesis." (PMID 40514675, 2025). "Overall, the TNF-IL-23-IL-17 pathway appears to be a critical link between psoriasis, its subtypes, and thyroid diseases, offering potential therapeutic targets for managing both conditions." (PMID 40922376, 2025). "This elevation of IFN-α, alongside Th1 cell migration, is likely to contribute to the paradoxical development of psoriasis during TNF antagonist therapy, necessitating further research to clarify these complex relationships." (PMID 40678000, 2025). "Altogether, this finding points out the importance of salt in diseases with elevated TNF-α levels, as is the case of psoriasis." (PMID 40005022, 2025). "Currently, while biologic therapies targeting TNF-α and IL-12/23 have demonstrated efficacy in treating both conditions, paradoxical effects, such as psoriasis exacerbation in IBD patients, highlight the need for alternative therapeutic approaches." (PMID 40406126, 2025). "The association between psoriasis and dyslipidemia is predicated on Th1-cell activation, autoantibodies against oxidized LDL, and the influence of cytokines (TNF-α, IL-1, and IL-6)." (PMID 40370872, 2025).
psoriasis (continued). "Megamonas was significantly elevated in psoriasis patients, correlating with pro-inflammatory cytokines (TNF-α, IL-6)." (PMID 40333159, 2025). "Erythrodermic psoriasis shares the TNF/IL-17A inflammatory axis with plaque psoriasis, but there is a unique immunophenotype of Th2/Th17 coactivation in erythrodermic psoriasis." (PMID 40303401, 2025). "Tumor Necrosis Factor (TNF) Inhibitors: TNF blockers (etanercept, adalimumab, etc.)are highly effective for moderate-severe psoriasis and PsA, and they were used early in our patient’s course." (PMID 40861474, 2025). "Leukocyte chemoattractants, such as TNF-α, play a vital role in the immunopathogenesis of psoriasis." (PMID 39997616, 2025). "The shared involvement of IL-17, IL-22, and TNF-α in psoriasis and AA underscores a common inflammatory pathway, though the therapeutic responses vary." (PMID 39859462, 2025). "Pathogens such as Staphylococcus aureus and HCV can trigger or exacerbate psoriasis, potentially through superantigen activation of skin-homing T cells and upregulation of tumor necrosis factor-α." (PMID 40546556, 2025). "We describe two cases of patients who developed two distinct cutaneous presentations of LE after 9–12 months of initiating anti‐TNF therapy (adalimumab) for the treatment of psoriasis." (PMID 39816706, 2025). "Since IL-10 inhibits production of pro-inflammatory cytokines such as IL-1, IL-6, and TNF-α, it can be useful for reducing inflammatory skin conditions, like psoriasis." (PMID 41465292, 2025). "Treatment with methotrexate and TNF-α inhibitors appears to be the most effective in reducing cardiovascular events in patients with psoriasis." (PMID 40584532, 2025). "Acitretin furthermore demonstrates immunomodulatory properties by diminishing the secretion of pro-inflammatory cytokines, such as IL-6 and TNF-α, which are pivotal in the pathogenesis of psoriasis." (PMID 40560394, 2025). "Meanwhile, Th1 lymphocytes were commonly known by generation of interferon-gamma (IFN-γ) and tumor necrosis factor-alpha (TNF-α) which contribute to inflammatory milieu in psoriasis." (PMID 40818978, 2025). "The present study revealed that, in this group of patients with moderate-to-severe psoriasis, biological therapy decreases TNF-α serum levels and the clinical severity scores of the PASI and DLQI after 12 weeks of treatment." (PMID 40699767, 2025). "TNF-α is a proinflammatory cytokine that plays a significant role in the pathogenesis of chronic inflammatory skin diseases, including psoriasis." (PMID 41002407, 2025). "Mechanistically, smoking exacerbates psoriasis through oxidative stress and activation of inflammatory pathways (NF-κB, JAK–STAT signaling), thus elevating key psoriasis-associated cytokines (TNF-α, IL-17, IL-23)." (PMID 40428224, 2025). "Tumor necrosis factor-α (TNF-α), a closely associated cytokine in psoriasis, selectively induces the initiation of the NLRP3 inflammasome through the TNFR/caspase-8 pathway even without an initial signal." (PMID 39925805, 2025). "The persistent immune activation characteristic of psoriasis, driven by cytokines such as tumor necrosis factor α (TNFα), interleukin (IL)-17, and IL-23, contributes to endothelial dysfunction, oxidative stress, and atherogenesis." (PMID 40698258, 2025). "TNF-α acts as a regulator of the IL-23/Th17 axis and promotes IL-23 production by dendritic cells in psoriasis, suggesting that it possesses pro-inflammatory properties." (PMID 40690118, 2025). "Regarding our study, the psoriasis rat group II had a higher TNF-α level than groups V, VI, and VII, which got anti-inflammatory treatment although not significantly different (p 0.05)." (PMID 38712377, 2025). "In summary, converging mechanistic and clinical evidence points to dysregulated cytokine signaling involving IL-17, IL-23, and TNF-α as a shared inflammatory axis linking psoriasis and AD." (PMID 41465136, 2025).
psoriasis (continued). "TNF-α inhibitors, including etanercept, infliximab, and adalimumab, represent the first class of biologics employed in psoriasis treatment, exhibiting substantial success in diminishing psoriatic plaques and enhancing quality of life." (PMID 40560394, 2025). "The substantial shift in research focus from psoriasis to TNF-α during this transformative period coincided with the clinical introduction of TNF-α inhibitors such as infliximab and etanercept." (PMID 41011289, 2025). "Recent evidence has clearly demonstrated that these epidermal CD8+ T-cells are the actual producers of the psoriasis signature cytokines IL-17, IL-22, and TNF-α that convey the skin changes characteristic of psoriasis." (PMID 40243413, 2025). "In contrast, the subgroup that used IL-17 inhibitors due to psoriasis aggravation exhibited drug retention comparable to that of the TNF inhibitor group." (PMID 40615873, 2025). "Tumour necrosis factor‐alpha (TNF‐α), in particular, plays a significant role in the development and persistence of psoriasis by promoting keratinocyte proliferation and stimulating T cell activation." (PMID 40478194, 2025). "Our cytokine analysis showed elevated levels of IL-6, IL-18, and IL-33, demonstrating a complex network of interactions in TNF inhibitor-induced psoriasis." (PMID 40678000, 2025). "Hypertension, cardiovascular disease, metabolic syndrome, fatty liver disease, diabetes mellitus, inflammatory bowel disease, psoriatic arthritis and others, most of which are Th17 and/or TNF-α dependent, have been reported in patients with psoriasis." (PMID 40584532, 2025). "Die TNF-Inhibitoren werden als Medikamente gegen Psoriasis eingesetzt, dennoch kommt es in etwa 5 % der Fälle zum Neuauftreten einer paradoxen Psoriasis unter Anti-TNF-Therapie." (PMID 39747696, 2025). "This initiates processes such as T-cell activation and increased release of inflammatory cytokines [e.g., TNF-α, IL-17, IL-23], which play a critical role in the pathogenesis of psoriasis." (PMID 40572655, 2025). "Although the precise role of TNF-α in the pathomechanism of psoriasis remains to be fully elucidated, the high therapeutic efficacy of TNF-α inhibitors strongly supports the pivotal role of this cytokine—alongside IFN-γ—in the disease’s pathogenesis." (PMID 40731810, 2025). "The consistent pattern of increased TNF-α, IL-6 and IL-17 levels supports the paradigm shift from viewing psoriasis as apurely cutaneous disease to recognizing it as a systemic immune-mediated disorder." (PMID 41393395, 2025). "All cases included in the IL-17 inhibitor subgroup for psoriasis aggravation were switchers from TNF inhibitors." (PMID 40615873, 2025). "In fact, studies have shown that patients with psoriasis tend to have higher serum levels of TNF-α, IL-6, and resistin." (PMID 40740781, 2025). "Across nine adults with moderate-to-severe psoriasis treated with a TNF-α inhibitor, paired analyses (Wilcoxon signed-rank, two-sided α = 0.05) demonstrated a marked clinical improvement over 12 weeks alongside the objective recovery of skin barrier function." (PMID 41303905, 2025). "SCFAs inhibit the NF–κB pathway and reduce the production of pro-inflammatory cytokines such as IL-1β, IL-6, and TNF-α, which can alleviate skin symptoms in psoriasis, acne, or HS." (PMID 41178942, 2025). "Remicade, Humira, Simponi, and Cimzia manage autoimmune conditions like inflammatory bowel disease and psoriasis by inhibiting TNF-α and TNFR1 interaction, thereby moderating inflammation and modulating immune responses." (PMID 40303401, 2025). "In psoriasis, TNF-α binds to tumor necrosis factor receptor 1 (TNFR1/TNFRSF1A) and receptor 2 (TNFR2), activating downstream NF-κB and MAPK signaling pathways." (PMID 40948748, 2025). "(IQR): 9.6 (6–18.3)], with less than a quarter on biologic psoriasis therapy for skin disease management (n = 13 (anti-TNFα n = 10, anti-IL17 n = 2, anti-IL12/23 n = 1)) at baseline." (PMID 39811778, 2025).